ALDH3B2 (aldehyde dehydrogenase 3 family member B2)
Description:
Oxidizes medium and long chain fatty aldehydes in lipid droplets into non-toxic fatty acids.
Synonyms: ALDH8
Tractability: PROTAC: ubiquitination databases record sites on it.
Gene: Protein-coding gene on chromosome 11 (67,662,155 to 67,681,224, reverse strand). Ensembl gene ENSG00000132746.
Subcellular location: Lipid droplet
Pathways (Reactome):
Metabolism: Sphingolipid catabolism
Gene Ontology:
Molecular function: aldehyde dehydrogenase [NAD(P)+] activity; protein binding; 3-chloroallyl aldehyde dehydrogenase activity; aldehyde dehydrogenase (NAD+) activity; long-chain fatty aldehyde dehydrogenase (NAD+) activity; medium-chain fatty aldehyde dehydrogenase (NAD+) activity; oxidoreductase activity; oxidoreductase activity, acting on the aldehyde or oxo group of donors, NAD or NADP as acceptor
Biological process: alcohol metabolic process; aldehyde metabolic process; lipid metabolic process; sphingolipid catabolic process; ethanol catabolic process
Cellular component: cytoplasm; lipid droplet; plasma membrane
Genetic constraint (gnomAD): Loss-of-function variants: 47 observed, 39.06 expected, observed/expected ratio (o/e) 1.2, 90% interval 0.95 to 1.53. The upper end of that interval is the gene's LOEUF score, 1.53, which puts it in group 6 of 6, group 1 being the genes least tolerant of losing a copy. Missense variants: 464 observed, 526.59 expected, observed/expected ratio (o/e) 0.88, 90% interval 0.82 to 0.95. Synonymous variants: 217 observed, 231.2 expected, observed/expected ratio (o/e) 0.94, 90% interval 0.84 to 1.05.
Homologues: Orthologues: chimpanzee ALDH3B2 (95% identical), macaque ALDH3B2 (95% identical), mouse Aldh3b2 (81% identical), pig ALDH3B2 (81% identical), rat Aldh3b2 (79% identical), mouse Aldh3b3 (78% identical), guinea pig ALDH3B2 (78% identical), dog ALDH3B2 (60% identical), tropical clawed frog aldh3b2 (59% identical), zebrafish aldh3b1 (54% identical), Drosophila melanogaster Aldh-III (51% identical), Caenorhabditis elegans alh-2 (24% identical), and 1 more. Paralogues in human: ALDH3B1 (83% identical), ALDH3A2 (50% identical), ALDH3A1 (49% identical), ALDH1A3 (28% identical), ALDH1A2 (26% identical), ALDH1L2 (26% identical), ALDH9A1 (26% identical), ALDH1B1 (25% identical), ALDH1A1 (25% identical), ALDH2 (25% identical), ALDH1L1 (24% identical), ALDH5A1 (24% identical), and 5 more.
Diseases named in the same sentence as ALDH3B2 in open-access papers:
ALDH3B2 is named in the same sentence as 22 diseases in open-access papers, as found by Europe PMC text mining. Sharing a sentence is not in itself a finding about the gene and the disease. The quoted sentences say what the papers report.
breast carcinoma (4 papers, 2016 to 2022). "Three variants, rs116638271 in ALDH3B2, rs77274510 in RP11-703H8.9, and rs117564384 in SCGB1D2 in the chromosome 11q13 region were significantly associated with ER+ breast cancer after correction for multiple testing." (PMID 27708667, 2016). "ALDH3B2 participates in an eleven metabolic gene signature-based prognostic model for clear cell renal cell carcinoma and a gene expression signature-based nomogram model in the prediction of breast cancer bone metastases." (PMID 34907179, 2021). "In summary, we retrospectively identified five bone metastases‐related genes (KRT23, REEP1, SPIB, ALDH3B2, and GLDC) and constructed a gene expression signature‐based nomogram (GESBN) model for breast cancer patients by bioinformatics analysis." (PMID 30575323, 2019). "Meanwhile, several other risk model genes were identified in this study (ST6GALNAC4, PLPP2, ELOVL1, HACD1, VAPB, CERS2, ALDH3B2, and HACD3) have not yet been explored in depth in breast cancer." (PMID 36059802, 2022).
esophageal squamous cell carcinoma (4 papers, 2017 to 2021). Esophageal squamous cell carcinoma (ESCC) is a type of esophageal carcinoma (EC) that can affect any part of the esophagus, but is usually located in the upper or middle third. "The gene polymorphism of ALDH3B2 is associated with the susceptibility of colorectal cancer and esophageal squamous cell carcinoma." (PMID 34907179, 2021). "Polymorphism in ALDH3B2 was reported to be associated with esophageal squamous cell carcinoma in a Chinese population." (PMID 32377192, 2020). "ALDH3B2 polymorphisms are related to the esophageal squamous cell carcinoma in the Chinese population." (PMID 33221754, 2020). "In this hospital-based case-control epidemiological study, we investigated the association between tagging SNPs of ALDH3B2 and the risk of developing esophageal squamous cell carcinoma in a Chinese population." (PMID 29299137, 2017).
cholangiocarcinoma (3 papers, 2021 to 2024). A carcinoma that arises from the intrahepatic biliary tree (intrahepatic cholangiocarcinoma) or from the junction, or adjacent to the junction, of the right and left hepatic ducts (hilar cholangiocarcinoma). "ALDH3B2 expression was significantly upregulated in perihilar cholangiocarcinoma tissues, which was also correlated with tumor stage in pCCA patients." (PMID 38903532, 2024). "ALDH3B2 promotes the proliferation and metastasis of cholangiocarcinoma by regulating ITGB1 expression." (PMID 38903532, 2024). "Similar to previous studies in the ALDH family, we observed that inhibition of ALDH3B2 expression can inhibit the proliferation and clonogenic ability of cholangiocarcinoma cells by inducing G1 phase arrest." (PMID 34907179, 2021). "We also studied the effect of ALDH3B2 knockdown on the metastatic ability of cholangiocarcinoma cells by tail vein injection." (PMID 34907179, 2021). "In two cholangiocarcinoma cell lines, overexpression of ALDH3B2 promoted cell proliferation and clone formation by promoting the G1/S phase transition." (PMID 34907179, 2021). "The results showed that ALDH3B2 knockdown inhibited the liver metastasis and lung metastasis of cholangiocarcinoma cells, and reduced the tumor burden of mice." (PMID 34907179, 2021). "Expression of ALDH3B2 in normal bile duct cell line HIBEpiC and cholangiocarcinoma cell lines including QBC-939, RBE and HCCC9810 were examined by Western Blot and qPCR." (PMID 34907179, 2021). "We first studied the effect of ALDH3B2 knockdown or overexpression on the proliferation ability of cholangiocarcinoma cells." (PMID 34907179, 2021). "In our study, we analyzed the effect of ALDH3B2 expression on the metastasis ability of cholangiocarcinoma cells." (PMID 34907179, 2021). "The results showed that inhibition of ALDH3B2 expression inhibited the migration and invasion ability of cholangiocarcinoma cells." (PMID 34907179, 2021). "In conclusion, our findings demonstrated that high expression of ALDH3B2 on cholangiocarcinoma promotes tumor metastasis by upregulating integrin β1 and upregulating the phosphorylation level of c-Jun, p38, and ERK." (PMID 34907179, 2021). "The role of ALDH3B2 on the EMT of cholangiocarcinoma cells was also evaluated." (PMID 34907179, 2021). "The results revealed that knockdown of ALDH3B2 promoted the expression of E-cadherin and inhibited the expression of N-cadherin and snail, indicating that ALDH3B2 may also promote the progression of cholangiocarcinoma by promoting EMT." (PMID 34907179, 2021). "Further survival analysis in intrahepatic cholangiocarcinoma (iCCA, n = 27), pCCA (n = 87) and distal cholangiocarcinoma (dCCA, n = 80) cohorts have revealed that ALDH3B2 was a prognostic factor of CCA and was an independent prognostic factor of iCCA and pCCA." (PMID 34907179, 2021). "The results showed that ALDH3B1 and ALDH3B2 were highly expressed in hilar cholangiocarcinoma, which indicated the important role of ALDH3 family in the development of cholangiocarcinoma." (PMID 34907179, 2021). "All these results indicated that ALDH3B2 played an essential role in the regulation of the cell migration, invasion, and EMT of cholangiocarcinoma." (PMID 34907179, 2021).
colorectal cancer (3 papers, 2020 to 2021). A primary or metastatic malignant neoplasm that affects the colon or rectum. "While ALDH3B2 was not shown as one of the hub genes in the development of CRPC, it may still have significance for cancer progression as specific ALDH3B2 variants were correlated with the risk for colorectal cancer (CRC)." (PMID 34572930, 2021).
lung adenocarcinoma (2 papers, 2019 to 2023). A carcinoma that arises from the lung and is characterized by the presence of malignant glandular epithelial cells. "Two unique ALDH3B2 peptides were detected in proteomic analysis of forty human lung adenocarcinoma cell lines." (PMID 31847104, 2019). "Moreover, some ALDH isozymes are known to be differently expressed in healthy and cancerous tissues (e.g., ALDH1A3) and literature data indicate elevated ALDH3B2 mRNA levels in lung squamous cell carcinoma and lung adenocarcinoma compared to healthy tissues." (PMID 31847104, 2019).
alcohol dependence (1 paper, 2020). Physical and psychological dependence on alcohol. "It was reported that DNA methylation of ALDH3B2 was associated with alcohol dependence." (PMID 32377192, 2020).
breast tumors (1 paper, 2015). "These signature genes are densely connected, among which several, such as ESR1, FOXA1, NQO1, GATA1, ALDH3B2, keratins, are well-known players driving the heterogeneity and carcinogenesis of breast tumors." (PMID 26404658, 2015).
chronic pancreatitis (1 paper, 2023). A chronic inflammatory process causing damage and fibrosis of the pancreatic parenchyma. "ALDH3B1, ENO1, ALDH2, GAPDH, and LDHC had significant differences among grades, while ALDH3B1, PKM, and ALDH3B2 differed among chronic pancreatitis histories." (PMID 36814901, 2023).
endometrial cancer (1 paper, 2024). Primary or metastatic malignant neoplasm involving the endometrium (mucous membrane that lines the endometrial cavity). "The proteomic profiling of endometrial cancer cell lines revealed that ECC-1 and RL95-2 shared the ALDH isoforms ALDH3A1, ALDH3A2, ALDH3B1, ALDH3B2, ALDH7A1, ALDH9A1, and ALDH18A1 in their proteome." (PMID 38893151, 2024).
infertile (1 paper, 2025). "They selected 4 CpG sites (within the genes PRICKLE2, ALS2CR12, ALDH3B2 and PTGIR) differentially methylated between patients and controls for further validation in 111 samples (55 infertile patients/with abnormal sperm parameters and 56 fertile controls)." (PMID 38717684, 2025).
perihilar cholangiocarcinoma (1 paper, 2021). "In perihilar cholangiocarcinoma, higher ALDH3B2 expression was associated with higher T stage, higher M stage, higher incidences of neural invasion and higher serum CA19-9 while high ALDH3B2 expression was associated with high serum CEA in iCCA or dCCA." (PMID 34907179, 2021). "We analyzed the expression of ALDHs in 8 paired tumor and peritumor perihilar cholangiocarcinoma (pCCA) tissues and found that ALDH3B1 and ALDH3B2 were upregulated in tumor tissues." (PMID 34907179, 2021).
Sepsis (1 paper, 2022). Sepsis is defined as life-threatening organ dysfunction caused by a dysregulated host response to infection. "A potentially suppressed conversion is supported by the finding that alcohol and aldehyde dehydrogenases Adh1 and Aldh1a7 gene expression was strongly suppressed by sepsis, although Aldh3b2 expression was increased." (PMID 35732826, 2022). "Hepatic gene expression of Adh1 and Aldh3b2, involved in the metabolism of 1,3-butanediol, was decreased by sepsis and largely unaffected by 3HHB treatment." (PMID 35732826, 2022).
cancer (9 papers, 2014 to 2025). A tumor composed of atypical neoplastic, often pleomorphic cells that invade other tissues. "ALDH3B2 was upregulated in PCa cells co-cultured with cancer-associated fibroblasts." (PMID 34572930, 2021). "However, little is known about ALDH3B2 in the development of cancer, especially CRC before this study." (PMID 32377192, 2020). "Moreover, we noticed that three upregulated genes in the high-risk group, ALDH3A1, ALDH3B2, and ADH7, participate in the cytochrome P450-mediated metabolism of trichloroethylene; trichloroethylene is an organic chemical, exposure to which can cause cancer." (PMID 32858528, 2020). "Aldehyde dehydrogenase (ALDH1B1, ALDH2, ALDH3B1, ALDH3B2, ALDH7A1 and ALDH9A1) were involved in the resistance against cyclophosphamide/carboplatin in cancer chemotherapy." (PMID 28225065, 2017).
tumor (5 papers, 2018 to 2024). "ALDH3B2 expression was associated with serum CEA in iCCA and dCCA, associated with tumor T stage, M stage, neural invasion and serum CA19-9 in pCCA." (PMID 34907179, 2021). "The expression of ALDH3B1 and ALDH3B2 was then verified with qPCR in paired tumor and peritumor iCCA, pCCA, and dCCA tissues (n = 6)." (PMID 34907179, 2021). "Among these differentially expressed ALDHs, ALDH3B1 and ALDH3B2 were highly expressed in tumor tissues compared with the peritumor tissues with the largest fold of changes." (PMID 34907179, 2021). "In conclusion, ALDH3B2 promotes tumor proliferation and metastasis in CCA by regulating the expression of ITGB1 and upregulating its downstream signaling pathway." (PMID 34907179, 2021). "ALDH3B2 is known to be a target of miR-143-5p, and an analysis of differential expression of microRNAs (miRNAs) and their potential targets in a publicly available PCa microarray datasets found miR-143-5p, a potential tumor suppressor, to be downregulated with a subsequent ALDH3B2 upregulation." (PMID 34572930, 2021). "It is possible that the product of the ALDH3B2 gene could serve as the enzyme protecting tumor colon cells from ROS (reactive oxygen species), considering that expression of other alcohol dehydrogenase isozymes (ADH1B and ADH1C) is decreased." (PMID 30967137, 2019). "In this study, the expression pattern of 19 ALDH family members in 8 paired pCCA tumor and peritumor tissues were first analyzed with mRNA sequencing and ALDH3B1 and ALDH3B2 was found upregulated in pCCA tissues." (PMID 34907179, 2021). "Knockdown of ALDH3B2 inhibited cell migration, invasion, and EMT in vitro, and restrained tumor metastasis in vivo." (PMID 34907179, 2021). "Some tumor type-specific DEs were observed for ALDH1L1, ALDH3B1, ALDH3B2, ALDH4A1 and ALDH7A1." (PMID 29426835, 2018).
colorectal (1 paper, 2020). "ALDH3B2 also plays an important role in colorectal carcinogenesis." (PMID 33221754, 2020).
ALDH3B2 also shares sentences with these, for which no sentence is quoted: alcoholic cirrhosis (1 paper); clear cell renal cell carcinoma (1); Fanconi Anaemia (1); intrahepatic cholangiocarcinoma (1); lung carcinoma (1); male infertility (1); ovarian carcinoma (1).